RB1CC1 (RB1 inducible coiled-coil 1)
Diseases named in the same sentence as RB1CC1 in open-access papers (continued):
Sharing a sentence is not in itself a finding about the gene and the disease.
cancer (21 papers, 2009 to 2025). A tumor composed of atypical neoplastic, often pleomorphic cells that invade other tissues. "WIPI2, ATG9B, MAP1LC3A, and RB1CC1 have higher frequencies of gain mutation frequencies in the pan-cancer analysis." (PMID 34636718, 2021). "ATG2B, ATG2A, ULK1, and RB1CC1 had a wide range of mutation frequencies in the pan-cancer analysis." (PMID 34636718, 2021). "We therefore performed a search for drugs that reinforce the function of RB1CC1, with the aim of identifying potential cancer therapeutic drugs." (PMID 35220675, 2022). "We next evaluated the expression of RB1CC1 in a series of cancer cell lines treated with RSL3 and erastin." (PMID 35220675, 2022). "Evaluation of RB1CC1 expression can provide useful clinical information on various cancers and neurodegenerative diseases." (PMID 22396748, 2012). "The use of chemotherapy was significantly higher in RB1CC1(−) patients than in RB1CC1(+) patients (p<0.0001), and was also higher in patients with triple-negative cancers than in those with non-triple-negative disease (Chi-square and Fisher's exact test, p<0.0001; data not shown)." (PMID 21203526, 2010). "Notably, real-time quantitative RT-PCR analysis revealed significant RB1CC1 mRNA overexpression vs. normal colonic mucosae in MSI-H cancers manifesting RB1CC1 3′UTR MSI (9.0-fold; p = 3.6×10−4)." (PMID 19888451, 2009). "It has been shown that the stage related gene RB1CC1 (RB1-inducible coiled-coil 1) can suppress cell cycle progression and inhibit proliferation through activating the promoter and expression of recurrence related gene RB1 in human cancer." (PMID 23658834, 2013). "Taken together, it is speculated that RB1CC1 may act as an oncogene in large intestine, and that 3′UTR MSI may serve as an upregulatory mechanism in place of genomic amplification in MSI-H cancers that typically lack chromosomal aberrations." (PMID 19888451, 2009).
infection (12 papers, 2014 to 2025). The state of being infected such as from the introduction of a foreign agent such as serum, vaccine, antigenic substance or organism. "This elucidates the potential role of RB1CC1 and ULK1 in early infection with SARS-CoV-2 and illuminates how NIC may regulate autophagy." (PMID 37901834, 2023). "However, we found that the autophagy kinase regulator RB1CC1 does not leave the nucleus during EV-D68 infection, indicating that SIRT-1 is being targeted for translocation." (PMID 37850626, 2023).
neurodegenerative disease (4 papers, 2012 to 2025). A disorder of the central nervous system characterized by gradual and progressive loss of neural tissue and neurologic function. "Consistent with the conclusion that the canine disorder is the result of the RB1CC1 29:4891014 C>T variant, variants in autophagy genes have been associated with a number of human autosomal recessive hereditary neurodegenerative diseases." (PMID 40149422, 2025).
psychiatric disorder (2 papers, 2023 to 2024). A disorder characterized by behavioral and/or psychological abnormalities, often accompanied by physical symptoms. "Multiple studies have associated FIP200 (FAK family kinase-interacting protein of 200 kDa, aka RB1CC1) with psychiatric disorders." (PMID 37137886, 2023).
myopathy (1 paper, 2025). A disease of the muscle in which the muscle fibers do not function properly. "For example, variants in RB1CC1 have been associated with differences in muscle strength in human subjects, and conditional rb1cc1 knockout in mice results in myopathy with the accumulation of inclusion bodies in muscle fibers." (PMID 40149422, 2025).
RB1CC1 also shares sentences with these, for which no sentence is quoted: cervical cancer (5 papers); glioblastoma (4); influenza (3); chronic pancreatitis (2); gastric cancer (2); osteosarcoma (2); age (1); autism spectrum disorder (1); Autoimmunity (1); bacterial infection (1); bladder cancer (1); cerebellar degeneration (1); Cerebral ischemia (1); clear cell renal carcinoma (1); colorectal cancer (1); COVID-19 (1); depressive disorder (1); developmental delay (1); esophageal squamous cell carcinoma (1); essential tremor (1); gastroenteritis (1); gram-negative bacterial infections (1); Hepatic steatosis (1); Hyperinsulinemia (1); Hypertension (1); infectious disease (1); injury (1); intrahepatic cholangiocarcinoma (1); ischemia (1); liver diseases (1).
A further 16 diseases each share a sentence with RB1CC1 in 1 paper.